PHB2 (prohibitin 2)
Description:
Protein with pleiotropic attributes mediated in a cell-compartment- and tissue-specific manner, which include the plasma membrane-associated cell signaling functions, mitochondrial chaperone, and transcriptional co-regulator of transcription factors and sex steroid hormones in the nucleus. In the mitochondria, together with PHB1, forms large ring complexes (prohibitin complexes) in the inner mitochondrial membrane (IMM) and functions as a chaperone protein that stabilizes mitochondrial respiratory enzymes and maintains mitochondrial integrity in the IMM, which is required for mitochondrial morphogenesis, neuronal survival, and normal lifespan (Probable). The prohibitin complex, with DNAJC19, regulates cardiolipin remodeling and the protein turnover of OMA1 in a cardiolipin-binding manner (By similarity). Also regulates cytochrome-c oxidase assembly (COX) and mitochondrial respiration. Binding to sphingoid 1-phosphate (SPP) modulates its regulator activity. Has a key role of mitophagy receptor involved in targeting mitochondria for autophagic degradation. Involved in mitochondrial-mediated antiviral innate immunity, activates RIG-I-mediated signal transduction and production of IFNB1 and pro-inflammatory cytokine IL6. In the nucleus, serves as transcriptional co-regulator (Probable). Acts as a mediator of transcriptional repression by nuclear hormone receptors via recruitment of histone deacetylases. Functions as an estrogen receptor (ER)-selective coregulator that potentiates the inhibitory activities of antiestrogens and represses the activity of estrogens. Competes with NCOA1 for modulation of ER transcriptional activity (By similarity). In the plasma membrane, is involved in IGFBP6-induced cell migration. Cooperates with CD86 to mediate CD86-signaling in B lymphocytes that regulates the level of IgG1 produced through the activation of distal signaling intermediates. Upon CD40 engagement, required to activate NF-kappa-B signaling pathway via phospholipase C and protein kinase C activation (By similarity). (Microbial infection) Involved in human enterovirus 71/EV-71 infection by enhancing the autophagy mechanism during the infection.
Synonyms: BAP; REA; BCAP37; Bap37; p22; PNAS-141; hBAP
Tractability: Antibody: UniProt places it where antibodies can reach, with high confidence; its Gene Ontology location is reachable by antibodies, with high confidence. PROTAC: ubiquitination databases record sites on it; its protein half-life has been measured.
Gene: Protein-coding gene on chromosome 12 (6,965,327 to 6,970,841, reverse strand). Ensembl gene ENSG00000215021.
Subcellular location: Mitochondrion inner membrane; Cytoplasm; Nucleus; Cell membrane; Mitochondrion inner membrane (Isoform 1); Mitochondrion inner membrane (Isoform 2)
Subcellular location (Human Protein Atlas): Mitochondria
Pathways (Reactome):
Cellular responses to stimuli: Cellular response to mitochondrial stress
Transport of small molecules: Processing of SMDT1
Gene Ontology:
Molecular function: binding; identical protein binding; protein binding; protein heterodimerization activity; protein homodimerization activity; sphingolipid binding; nuclear estrogen receptor binding
Biological process: antiviral innate immune response; cell migration; mitochondrion organization; mitophagy; negative regulation of apoptotic process; negative regulation of DNA-templated transcription; positive regulation of ERK1 and ERK2 cascade; positive regulation of MAPK cascade; protein import into nucleus; protein stabilization; regulation of complement activation; regulation of transcription by RNA polymerase II; RIG-I signaling pathway; sister chromatid cohesion; B cell activation; positive regulation of immunoglobulin production; positive regulation of non-canonical NF-kappaB signal transduction; regulation of cardiolipin metabolic process
Cellular component: cell periphery; cell surface; cytoplasm; mitochondrial inner membrane; mitochondrial outer membrane; mitochondrial prohibitin complex; mitochondrion; nuclear matrix; nucleus; plasma membrane; protein-containing complex; inner mitochondrial membrane protein complex; membrane
Genetic constraint (gnomAD): Loss-of-function variants: 16 observed, 37.49 expected, observed/expected ratio (o/e) 0.43, 90% interval 0.29 to 0.65. The upper end of that interval is the gene's LOEUF score, 0.65, which puts it in group 2 of 6, group 1 being the genes least tolerant of losing a copy. Missense variants: 249 observed, 309.12 expected, observed/expected ratio (o/e) 0.81, 90% interval 0.73 to 0.89. Synonymous variants: 130 observed, 127.07 expected, observed/expected ratio (o/e) 1.02, 90% interval 0.89 to 1.18.
Homologues: Orthologues: chimpanzee PHB2 (100% identical), guinea pig PHB2 (100% identical), mouse Phb2 (100% identical), rabbit PHB2 (100% identical), rat Phb2 (99% identical), macaque PHB2 (99% identical), dog PHB2 (98% identical), pig PHB2 (98% identical), tropical clawed frog phb2 (90% identical), zebrafish phb2b (81% identical), zebrafish phb2a (78% identical), Drosophila melanogaster Phb2 (70% identical), and 1 more. Paralogues in human: PHB1 (47% identical).
Diseases named in the same sentence as PHB2 in open-access papers:
PHB2 is named in the same sentence as 129 diseases in open-access papers, as found by Europe PMC text mining. Sharing a sentence is not in itself a finding about the gene and the disease. The quoted sentences say what the papers report.
breast carcinoma (27 papers, 2015 to 2025). "Akt2 on the other hand was shown to interact with Prohibitin 2/Repressor of Estrogctivator (PHB2/REA) which has been implicated in transcriptional repression of myogenesis in estrogen-dependent cancers like breast cancer." (PMID 34298660, 2021). "Immunohistochemical clinicopathological evidence revealed that high BIG3 expression levels and low PHB2 phosphorylation levels are strongly associated with a poor prognosis in patients with ERα-positive breast cancers." (PMID 28555617, 2017). "The released PHB2 binds to the nuclear and cytoplasmic ERα, and blocks E2-associated signaling pathways, thereby inhibiting the proliferation of ERα-positive breast cancer cells in vitro and in vivo." (PMID 27657126, 2016). "Our previous studies demonstrated that endogenous BIG3 mainly localized in cytoplasm and sequesters PHB2, thereby causing the loss of function of PHB2 and resulting in constitutive ERα transcriptional activation in breast cancer cells." (PMID 26052702, 2015). "For instance, PHB2 acts as a tumour suppressor in breast cancer by interacting with estrogen receptor-alpha (ERα) in the nucleus, where it functions as a corepressor, inhibiting ERα-mediated transcription and proliferation." (PMID 38200519, 2024). "In this study, we identified PHB2 as the bona fide interacting partner of LacRNA, and the LacRNA-PHB2 complex was found to exert an inhibitory effect on breast cancer metastasis through c-Myc." (PMID 36782197, 2023). "Another paper reported a controversial oncogenic function of PHB2 in MCF7 (a breast cancer cell line with estrogen, progesterone, and glucocorticoid receptors) cells." (PMID 37190120, 2023). "PHB2 executes tumor suppressive activity in breast cancer (BC) through its involvement with ERα (estrogen receptor-alpha)." (PMID 37190120, 2023). "PHB2 was discovered as a tumor suppressor in breast cancer, osteosarcoma, and head and neck squamous cancer." (PMID 37190120, 2023). "The BIG3-PHB2 interaction happens between the A-inhibited guanine nucleotide-exchange protein 3 (BIG3) and prohibitin 2 (PHB2) in the cytoplasm of breast cancer cells." (PMID 35956774, 2022). "Since PHB1 and PHB2 were reported to regulate ERα signaling, which is a central oncogenic pathway in luminal breast cancer, we focused on the implication of PGRMC1 in the ERα signaling network and its possible involvement in breast cancer promotion." (PMID 34830790, 2021). "Collectively, it is expected that a therapeutic strategy targeting the interaction between BIG3 and PHB2 will be effective for breast cancer, with few serious adverse effect." (PMID 34285339, 2021). "For luminal breast cancer, PHB2 has been discussed as a potential tumor suppressor since its overexpression significantly diminished ERα signaling, whereas its downregulation elevated the latter." (PMID 34830790, 2021). "Similar to ERAP, XN prevents the growth of breast cancer cells that are positive for ERα by disrupting the interaction between PHB2 and BIG3." (PMID 34868199, 2021). "PHB2 repressed the proliferation of breast cancer cells that were positive for ERα by decreasing phosphorylated Akt, MAPK, and ERα, and by HER2, EGFR, and IGF-1Rβ inhibition." (PMID 34868199, 2021). "In estrogen receptor (ER)-positive breast cancer, PHB2 acts as a tumor inhibitor to suppress the growth of breast cancer cells by repressing the estrogen/ER signaling pathway." (PMID 29367618, 2018). "BIG3 is highly expressed in breast cancers and its interaction with PHB2 results in constitutive activation of E2/ERa signalling." (PMID 28555617, 2017). "Recent findings show that the brefeldin A-inhibited guanine nucleotide-exchange protein 3-prohibitin 2 (BIG3-PHB2) complex plays a crucial role in E2/ERα signalling modulation in breast cancer cells." (PMID 28500289, 2017).
breast carcinoma (continued). "According to these findings, we established a therapeutic strategy for breast cancer utilizing the tumour-suppressive activity of PHB2 upon its release from BIG3 via the dominant negative peptide ERAP, which targets the BIG3-PHB2 interaction." (PMID 28500289, 2017). "We found that overexpressed PHB2 interacted with KPNA1, KPNA5, and KPNA6, thereby leading to the E2-dependent translocation of PHB2 into the nuclei of breast cancer cells." (PMID 26052702, 2015). "Subsequently, we evaluated the possibility of the ERα-dependent nuclear translocation of PHB2 in the presence of E2 in breast cancer cells as previously reported." (PMID 26052702, 2015). "We recently reported that brefeldin A-inhibited guanine nucleotide-exchange protein 3 (BIG3) binds Prohibitin 2 (PHB2) in cytoplasm, thereby causing a loss of function of the PHB2 tumor suppressor in the nuclei of breast cancer cells." (PMID 26052702, 2015). "Here, we report that BIG3 blocks the estrogen (E2)-dependent nuclear import of PHB2 via the karyopherin alpha (KPNA) family in breast cancer cells." (PMID 26052702, 2015). "Our previous studies identified that brefeldin A-inhibited guanine nucleotide-exchange protein 3 (BIG3) interacts and co-localizes with PHB2 in the cytoplasm of breast cancer cells." (PMID 26052702, 2015). "More importantly, knockdown of each endogenous KPNA by siRNA caused a significant inhibition of E2-dependent translocation of PHB2 in BIG3-depleted breast cancer cells, thereby enhancing activation of estrogen receptor alpha (ERα)." (PMID 26052702, 2015). "In breast cancer, PHB2 represses estrogen and acts as a tumor suppressor." (PMID 40940954, 2025). "Notably, PHB2 is able to bind specifically to the ERα wildtype (WT) and common ERα mutants found in breast cancer." (PMID 40940954, 2025). "In breast cancers, PHB2 exhibits tumour-suppressive functions by inhibiting cell proliferation." (PMID 38200519, 2024). "In contrast, LacRNA may significantly reduce the level of c-Myc protein through PHB2 and inhibit the migration and invasion of breast cancer cells." (PMID 36782197, 2023). "We found that c-Myc was readily detected in PHB2 immunoprecipitants in breast cancer cells." (PMID 36782197, 2023). "The interaction between BIG3 and PHB2 (BIG3-PHB2) is important in breast cancer and osteosarcoma." (PMID 37190120, 2023). "Surprisingly, PHB2 expression was positively correlated with LacRNA levels in breast cancer cells." (PMID 36782197, 2023). "LacRNA and PHB2 expression was much higher in three luminal type breast cancer lines with low metastatic potential (MCF7, T47D, and BT-474) than in five highly metastatic HER2-enriched and triple-negative breast cancer cell lines (SK-BR-3, MDA-MB-468, BT-549, MDA-MB-231, and LM2)." (PMID 36782197, 2023). "Thus, LacRNA exerts its tumor suppressor function by inhibiting c-Myc by stabilizing PHB2 in breast cancer cells." (PMID 36782197, 2023). "In a 2022 paper, it was discovered that PHB2 in the cell membrane may function as a biomarker for precise diagnosis of the luminal A breast cancer cell subtype." (PMID 37190120, 2023). "Moreover, we validated the correlation between LacRNA and PHB2, c-Myc and its downstream pathways by analyzing RNA-seq data from 1094 patients with breast cancer from TCGA database." (PMID 36782197, 2023). "Overexpression of PHB2 had been reported in hepatocarcinoma, breast cancer as well as lung cancer." (PMID 35692054, 2022). "In contrast, in breast cancer cells, PHB2 interacts with BIG3 in the cytoplasm." (PMID 34868199, 2021). "Notably, the effects of PHB2 on tumor proliferation are different in estrogen receptor (ER)-positive breast cancer." (PMID 33537079, 2021). "In addition to wild type (WT) ERα, PHB2 can bind to ERα mutants, such as D538G and Y537S, which are often present in breast cancers that are resistant to hormonal therapy." (PMID 34868199, 2021).
breast carcinoma (continued). "However, little is known regarding the mechanism by which BIG3 inhibits the nuclear translocation of PHB2 into breast cancer cells." (PMID 26052702, 2015). "To further validate the KPNA-mediated E2-dependent nuclear translocation of endogenous PHB2 in breast cancer cells, we examined the knockdown effect of each KPNA via siRNA treatment on the subcellular distribution of endogenous PHB2 in MCF-7 cells after BIG3 knockdown followed by E2 treatment." (PMID 26052702, 2015). "Thus, understanding the regulation of the nuclear translocation of this PHB2 co-repressor is critical to further elucidate the E2 stimulus-dependent cell proliferation of ERα-positive breast cancers." (PMID 26052702, 2015). "However, this is controversial because endogenous PHB2 is abundantly expressed in ERα-positive breast cancer cells." (PMID 26052702, 2015). "Therefore, further analyses are needed to elucidate the involvement of endogenous KPNB in PHB2 nuclear-translocation in breast cancer cells." (PMID 26052702, 2015). "Understanding this regulation of PHB2 nuclear import may provide therapeutic strategies for controlling E2/ERα signals in breast cancer cells." (PMID 26052702, 2015). "Thus, LacRNA could change the protein level of PHB2 in the cytoplasm of breast cancer cells, and we explored whether LacRNA could influence the protein stability of PHB2." (PMID 36782197, 2023). "It has been reported that PHB2 enhances the proliferation and tumorigenicity of CRC cells, promotes the migration and invasion of lung cancer cells, and affects tamoxifen resistance in breast cancer cells, suggesting that PHB2 dysregulation may play multiple functions in tumors." (PMID 37907779, 2023). "Phosphorylated PHB2 translocates to nuclear ERα and plasma membrane-type ERα in an E2-dependent manner, resulting in multiple suppression of E2-dependent transcriptional activity and membrane-type ERα-mediated nongenomic signaling (various phosphorylation cascades) in ERα-positive breast cancer." (PMID 34285339, 2021). "Targeting PHB2 interactions with other molecules may be a potential treatment for breast cancer." (PMID 34868199, 2021). "However, the mechanism by which BIG3 blocks E2-dependent PHB2 nuclear translocation in breast cancer cells remains unclear." (PMID 26052702, 2015). "Because previous reports have shown that PHB2 has a putative nuclear localization signal (NLS) at 86-RPRK-89, we hypothesized that PHB2 is translocated to the nucleus via its interaction with Karyopherin-alpha family (KPNAs, importin-alpha) proteins in breast cancer cells." (PMID 26052702, 2015). "We have recently demonstrated in breast cancer cells, that progestin-activated PGRMC1 interacts with PHB1/PHB2 resulting in enhanced ERα-dependent transcription and cell proliferation." (PMID 38308254, 2024). "The large majority (10/13) of these genes were reported to play a role in the regulation of estrogen and/or progesterone response in human breast cancer (NCOA7:; NCOA3:; USP22:; MED24:; CCAR1:; CRY2:; STAT5B:; PAGR1:; TAF1:; PHB2:)." (PMID 35996163, 2022). "Using ERAP to disrupt the interaction between PHB2 and BIG3 can stop breast cancer cells that are positive for ERα from growing and make these cells more responsive to tamoxifen." (PMID 34868199, 2021). "Treatment of breast cancer cell lines with ERAP led to rapid dissociation of PHB2 captured by BIG3 and thereby rapid, E2-dependent PHB2 phosphorylation at Ser39, allowing reactivation of the innate suppressive capability of PHB2." (PMID 34285339, 2021). "In contrast, a flavonoid, xanthohumol, showed potent anti-cancer activity against luminal-type breast cancer by inhibiting the interaction between the growth of luminal-type guanine nucleotide-exchange protein 3 (BIG3) and tumor suppressor prohibitin 2 (PHB2)." (PMID 27657126, 2016).
breast carcinoma (continued). "Here we report the mechanism by which BIG3 blocks the nuclear translocation of PHB2 via interactions with multiple karyopherin alpha (KPNA) proteins, including KPNA1, KPNA5, and KPNA6, in ERα-positive breast cancer cells." (PMID 26052702, 2015). "Taken together, these findings suggest that BIG3 structurally overlays each KPNA binding region of PHB2, thereby blocking PHB2-KPNA interactions and resulting in the inhibition of E2-dependent PHB2 nuclear translocation in breast cancer cells." (PMID 26052702, 2015). "The authors did not acknowledge PHB2’s tumor suppressor function in breast cancer and no explanation of the discrepancy was discussed in this paper." (PMID 37190120, 2023). "To identify responsible factors that are involved in oncogenic signaling of HR positive breast cancer cells, we performed Co-IP with HA-PGRMC1 followed by mass spectrometry and identified PHB1 and PHB2 as possible PGRMC1 interaction partners upon treatment with NET." (PMID 34830790, 2021). "Prohibitin 2 (PHB2), also known as REA3, functions as both a modulator of the E2/ERα signalling network and a corepressor of ERα; however, its abundant expression in ERα-positive breast cancers is not well understood." (PMID 28555617, 2017). "In breast cancers, however, BIG3 captures PHB2 through its KPNA (KPNA1, KPNA5, and KPNA6)-binding region(s), thereby inhibiting the E2-dependent suppressive ability of PHB2." (PMID 26052702, 2015). "Taken together, these findings suggestd that stERAP-6 exhibited sustained inhibition of BIG3-PHB2 complex formation in tumours, thereby releasing PHB2 and allowing suppression of both genomic and non-genomic ERα activation along with E2-induced breast cancer growth in vivo." (PMID 28500289, 2017). "However, the pathophysiological role of BIG3 in the inactivation of PHB2 suppressive activity in breast cancer cells has not been elucidated." (PMID 28555617, 2017). "Accordingly, these evidences indicate the possibility that the role of KPNA2 binding to PHB2 may be independent of nuclear transport in breast cancer cells." (PMID 26052702, 2015). "In particular, the discovery that stERAP enables reactivation of the innate tumor-suppressive activity of PHB2 based on this molecular mechanism may lead to therapeutics that greatly contribute to the treatment of refractory breast cancer without impairing the quality of life of patients." (PMID 34285339, 2021). "Notably, endogenous PHB2 preferentially bound to BIG3 in MCF-7 cells regardless of the abundant presence of KPNAs, suggesting the possibility that endogenous PHB2 has a high affinity to BIG3 protein compared with that to KPNAs in breast cancer cells." (PMID 26052702, 2015).